SMAD3 (SMAD family member 3)
Diseases named in the same sentence as SMAD3 in open-access papers (continued):
Sharing a sentence is not in itself a finding about the gene and the disease.
tumor (continued). "Previous studies have revealed that Smad3 signalling pathway plays important roles in EMT, stemness and metastasis of tumours." (PMID 37723905, 2023). "KLF4 is a Yamanaka factor important for pluripotency, while SMAD3 is essential for TGFB1 signaling, and PPARG has complex roles in tumor metabolism and immunity; they have known roles as positive and negative regulators of EMT and bladder carcinogenesis." (PMID 38129585, 2023). "SMAD4 has tumor suppressor activity, and, in its absence, the SMAD2/SMAD3 heterodimer mediates the oncogenic effects of TGFB by activating a SMAD4-independent signaling pathway." (PMID 37509254, 2023). "On the one hand, as a tumor suppressor, miR-15A binds to the 3′non-coding end (3′-UTR) of Smad3 and inhibits its activity." (PMID 36936418, 2023). "It seems that impairment of the MENIN protein blocks the transcriptional effects mediated by Smad3 and TGF-b, which can lead to inadequate cell growth and tumor onset." (PMID 36967793, 2023). "To elucidate the potential regulatory role of Smad3 in neutrophil development in TME, we performed RNA velocity analysis to recapture the developmental pathway of Smad3-WT and -KO TANs in LLC tumor with single-cell resolution." (PMID 37002229, 2023). "The univariate Cox regression analysis revealed that SMAD2, SMAD3, TNM staging system, and tumor stage were independent prognostic factors in liver patients in TCGA." (PMID 37790613, 2023). "Our results are generally consistent with previous reports, suggesting that SMAD3 and SMAD4 can act as tumor suppressor genes of CRC and influence patient immune status." (PMID 36969909, 2023). "EA specifically interferes with several signaling cascades, including PI3K/AKT, NF‐B, CDK6, TGF‐/Smad3, and AKT/mTOR, to perform its anti‐tumor actions." (PMID 38107139, 2023). "In an in vitro experiment, inhibition of SMAD3 C-terminal phosphorylation reversed ABCB1- and ABCG2-mediated multidrug resistance in cancer cell lines, E4BP4-mediated NK cell development, and tumor metastasis." (PMID 35085106, 2022). "Taken together, these findings suggest that cancer progression is related to increased pro-tumorigenic SMAD3 signaling, which prevails over SMAD2 signaling in the hypoxic tumor microenvironment." (PMID 35681731, 2022). "We identified macrophage-specific Smad3 as a pivotal regulator for promoting MNT at the genomic level; its disruption effectively blocked the tumor innervation and cancer-dependent nocifensive behaviors in vivo." (PMID 36206343, 2022). "In our previous work, we observed a marked reduction of tumor-friendly elements including angiogenesis, matrix metalloproteinase (MMP) production, and regulatory T cells in the Smad3-null or Smad3-inhibited TME." (PMID 36206343, 2022). "Meanwhile, GDF-10 can activate the TGFBR1/Smad3/ERK pathway to promote the growth and migration of tumor cells, and further regulate the recruitment and activation of Smad family transcription factors." (PMID 36714584, 2022). "In conclusion, our results revealed that TGF-β regulates LINC00152 transcription via SMAD3 and maintains its stability through HuR, upregulating LINC00152 expression in LUAD tumor tissues." (PMID 36071042, 2022). "Meanwhile, EV-TβRII as cargo delivered to CD8+ T cells induces the activation of SMAD3 which cooperates with TCF1 transcription factors to impose CD8+ T cell exhaustion and dysregulation of anti-tumor immunity." (PMID 35915084, 2022). "When STAT3 is aberrantly activated in tumours, STAT3 selectively and directly interacts with Smad3, sequesters Smad3 from the Smad nucleoprotein complex and thus antagonizes TGF-β signalling." (PMID 35655269, 2022). "Encouragingly, pharmaceutical inhibition of Smad3 markedly suppressed MNT and the overall neurogenesis in tumor." (PMID 36206343, 2022). "While Smad3 elicits pro-tumor functions by enhancing EMT, invasion and angiogenesis, Smad2 displays opposite effects in many scenarios to suppress tumor progression." (PMID 35794621, 2022).
tumor (continued). "Downstream of the TGF-β pathway, SMAD3 and CTNNB1 form a complex with other molecules in the nucleus and induce EMT, proliferation, and angiogenesis in desmoid tumor cells via the SMAD2/3 pathway." (PMID 36497457, 2022). "An in vivo rescue experiment was performed and we observed that overexpressing SMAD3 in MDA-MB-231 YTHDC1 KO cells restored metastasis in the lungs, with little effect on primary tumor size." (PMID 35966596, 2022). "PCBP1 interacts with phosphorylated SMAD3 to regulate splicing of CD44 and promote tumor metastasis." (PMID 36071042, 2022). "Encouragingly, targeting the MMT key regulator Smad3 effectively blocked the production and protumoral actions of CAF, evidencing its translational potential as a novel therapeutic target in the tumour microenvironment for cancer." (PMID 34791825, 2022). "The functions of SMAD3 in HCC were still controversial; some reports showed that it was a tumor suppressor, while others proposed that it was a tumor promoter." (PMID 35123494, 2022). "In nonmalignant epithelial cells with intact TGF-β pathway signaling, TGF-β is antiproliferative, and neutralization is expected to result in decreased tumor cell phosphorylated SMAD2 (p-SMAD2), p-SMAD3, and p21 and increased Ki67 (a marker of proliferation)." (PMID 35727629, 2022). "The combination treatment significantly reduced the expressions of p-AKT, p-PI3K, Smad2, Smad3, p-JNK, p-ERK, and NF-κB in tumor tissues, all of which are signaling molecules involved in TGF-β1-induced EMT." (PMID 34948368, 2021). "Smad2, Smad3, Smad4, and COL1A1 proteins were strongly expressed in tumor tissues from CRC patients compared with normal colon controls." (PMID 34966673, 2021). "The change in Smad3 partners affected its regulation of downstream genes, which prompted TGF-β to play an opposite role in regulating glucose metabolism of tumor cells in normoxia and hypoxia." (PMID 34930376, 2021). "Based on CRISPR screen, data mining, and in vivo experiments, we identified and validated three genes (SMAD3, BIRC3, and SLC9A5) able to promote both BRAFi‐resistance and tumor growth." (PMID 33724679, 2021). "For example, transforming growth factor β (TGFβ) has been reported to activate NFAT, which in turn displaces SMAD family member 3 (SMAD3) repressor complexes allowing for the upregulation of MYC and ultimately promoting tumor growth." (PMID 33919156, 2021). "Further downstream, YAP can bind Smad3 to form a YAP-TEAD4–Smad3-p300 complex on the promotor of CTGF, a cytokine involved in EMT and tumor progression." (PMID 34712672, 2021). "The present results show that the tumor tissues of TNBC mice treated with a combination of low-dose Avastin and FO with Se have significantly lower levels of Smad2/Smad3 phosphorylation, Smad4, and TMEPAI than those of mice treated with Avastin alone." (PMID 33805447, 2021). "Our experiments demonstrated BBR increased p-Smad2 and decreased p-Smad3 by binding to TGFβR1 and TGβFR2 inhibiting TGF-β/Smad, then, PI3K/AKT and other signaling pathways to restrain EMT, metastasis, and invasion in tumor cells." (PMID 34712379, 2021). "To further examine the role of SMAD3 in our tumor model, we implanted PANC-1 cells with SMAD3 knockdown in orthotropic mice models." (PMID 34439202, 2021). "The downregulation of Rap1GAP expression can activate the TGF-β/Smad3 pathway to inhibit NIS expression and alter the tumor cell functions of PTC." (PMID 34840979, 2021). "In PANC-1 cells, PLEXIND1 downregulation results in a decrease in protein expression of the SMAD3 and mRNA levels of SMAD7 and Serpine1, potentially abetting tumor suppression." (PMID 34439202, 2021). "For proneural GSCs, pharmacologic blockade of HIF-1α activity by GN44028 and of Smad3 activity by the Smad3 inhibitor, (E)-SIS3 or a palmitoylation inhibitor, 2-BP, effectively suppressed tumor growth and extended survival rates in animals with xenografts." (PMID 34707087, 2021).
tumor (continued). "The results of anti-TGF-β1 and anti-p-Smad3 IHC assays showed that, relative to vehicle and anti-PD-L1, YM101 lowered the expressions of TGF-β1 and p-Smad3 in the EMT-6 tumor model." (PMID 33593403, 2021). "SMAD3 is a key transcriptional modulator of the TGF-β/SMAD pathway, which plays a critical role in TGF-β-mediated EMT and tumor metastasis 25,26." (PMID 33033523, 2020). "The results validated that down-regulation of HDAC3 or TGIF1, or up-regulation of miR-296-3p resulted in suppressed tumor growth, elevated apoptosis rate and inhibited TGF-β1, Smad2 and Smad3 expression." (PMID 33203425, 2020). "Dysfunction of the TGF-β–regulated SPTBN1/SMAD3/CTCF complex increases stem cell–like properties in HCC cells and enhances tumorigenesis in tumor-initiating cells in a mouse model." (PMID 33457451, 2020). "Taken together, these results suggest that smoking-mediated upregulation of miR-216b increases NSCLC cell growth by downregulating Smad3 and inhibiting TGF-β-induced tumor suppressor function, and induces resistance to platinum-based therapy." (PMID 32668597, 2020). "SMAD3 is related to the transforming growth factor-β (TGF-β) signaling pathway, which is connected to tumor development." (PMID 33036415, 2020). "Our previous study showed that low-dose and long-term CSC treatment downregulates Smad3 protein expression, resulting in inhibition of TGF-β signaling and decrease in TGF-β-mediated tumor suppressor functions in NSCLC." (PMID 32668597, 2020). "Together these data demonstrate that despite differences in the genetic backgrounds of TNBC tumor cells, ZNF165 and SMAD3 exhibit significant co-occupancy on chromatin throughout the genome." (PMID 32515734, 2020). "One study demonstrated that VEGF and TGFBR1 (ALK5) inhibitors can synergistically promote tumor angiogenesis by potentially blocking the downstream effectors of ALK5 such as Smad2 and Smad3." (PMID 32993787, 2020). "In contrast, in the invasive front of tumor cells undergoing TGF-β-induced EMT, SETDB1 expression is repressed by TGF-β to de-repress the Smad3-SETDB1-mediated repression of the Snail promoter." (PMID 32114978, 2020). "PJA1 overexpression is detected in HCCs and is sufficient to suppress SMAD3- and SPTBN1-mediated TGF-β tumor suppressor signaling, promoting HCC proliferation." (PMID 33457451, 2020). "Increased expression of pSMAD2/3 (phosphorylated SMAD2 and SMAD3) and PAI-1 (plasminogen activator, TGF-β1 target gene) was observed in more differentiated ccRCC tumor samples and correlated with a larger tumor size and lower patient survival rate." (PMID 31842336, 2019). "ARID1A, as a tumor suppressor, regulates CDKN1A and SMAD3 transcription and tumor growth by collaborating with p5344." (PMID 31772679, 2019). "TGF‐β is known to regulate the expression of MMPs via Smad and non‐Smad pathways in tumor stromal cells; TGF‐β and p‐Smad3 were also elevated in syncytiotrophoblast on day 5, suggesting that they play a role in regulation of MMP expression in the placenta." (PMID 31424120, 2019). "We stained sequential tumor sections by IHC with a commercial anti-integrin β6 antibody, AN03 and phosho-SMAD3." (PMID 30696911, 2019). "Restoring IFN-β signaling to OSM-driven CSC re-engages IFN-β-mediated differentiation by repressing OSM/STAT3/SMAD3-mediated SNAIL expression, tumor initiation, and growth." (PMID 31036052, 2019). "By using in vitro cell line models, we reveal that ONECUT2 regulates the aggressive tumor biology in NEPC, at least partially through activating SMAD3-HIF1α signaling." (PMID 30655535, 2019). "The blocking of Slit2/Robo1 signaling by R5 attenuated TGF-β1 phosphorylation of Smad2 and Smad3 in Lovo cells, SW480 cells, and tumor tissues of ApcMin+ mice compared with mIgG-treated groups." (PMID 31242633, 2019).
tumor (continued). "The tumor lysates of five TNBC patients (BC1-BC5) and four normal/benign tissues (N1-N4) showed similar differences in Smad2 and Smad3 protein expression levels in tumors vs normal/benign tissues as was noted in established cell lines." (PMID 31798766, 2019). "Taken together, our results suggest that TGF-β1 knockdown inhibits tumor growth and increases chemosensitivity by promotion of BRCA1/Smad3 signaling." (PMID 30594239, 2018). "High SMAD3 levels are required for the tumor suppressive effects of TGF-β, while lower expression levels correlate with the tumor-promoting effect of TGF-β." (PMID 30761216, 2018). "We show for the first time that knockdown of TGF-β1 suppresses tumor growth and promotes the chemosensitivity of OC cells to cis-platinum, in that we observed a BRCA1 expression increase and the activation of Smad3." (PMID 30594239, 2018). "TGF-β acts as a tumor suppressor during the early stages of tumorigenesis, and the ability of TGF-β/SMAD3 signal in tumor suppression has been demonstrated by multiple studies." (PMID 29633893, 2018). "The systemic treatment of SIS3 significantly inhibited the phosphorylation of Smad3 in both LLC and B16F10 tumour tissues and suppressed cancer progression in a dosage-dependent manner, resulting in a 100% survival rate." (PMID 28262747, 2017). "The cumulative results show the intricate transcriptional regulation of FOXP3 is controlled by three transcription factors, SMAD3, GATA3, and RUNX3, involving CNSs and promoter regions of FOXP3 in tumor-induced CD8+ Treg cells." (PMID 28487507, 2017). "Depletion of NK cells from SIS3-treated B16F10 tumour-bearing mice partially reversed the antitumour effects of SIS3, which further supports the promoting role of Smad3-mediated NK suppression in cancer progression." (PMID 28262747, 2017). "A similar function in HCC has also been illustrated for both of SMAD3 and RBL2 in the previous studies 43, 44, suggesting the significant function of SMAD3 and RBL2 as a tumor suppressor in HCC." (PMID 28639733, 2017). "Our results also suggest that the transcriptional regulation of FOXP3 is controlled by three transcription factors, SMAD3, GATA3, and RUNX3, in a concerted manner involving CNSs and promoter regions of FOXP3 in tumor-induced CD8+ Treg cells." (PMID 28487507, 2017). "Here the authors show that Smad3 inhibits NK cell differentiation and effector function by repressing NFIL3, and that genetic or pharmacological blockade of Smad3 expands tumour-suppressive NK cells and restricts tumour growth in mice." (PMID 28262747, 2017). "Inhibition of Smad3 also enhanced anticancer activities of NK cells by increasing releases of granzyme B, IL-2 and IFN-γ locally within the tumour tissues and systemically in the circulation." (PMID 28262747, 2017). "Further studies are required to elucidate the relationship between Smad3 and HIF-1α, such as the effect of this interaction on HIF-1α stabilization, during tumor glycolysis and tumor progression." (PMID 28471448, 2017). "As expected, only a small population of tumour cells showed co-expression of PEG10 and p-SMAD3 or PEG10 and pSMAD1/5." (PMID 29044189, 2017). "Relatively higher expressions of TGF-β1, CTGF, p-Smad3, p-ERK1/2 and CD44 protein were observed in xenograft tumor treated with TMZ." (PMID 28617438, 2017).
tumor (continued). "The crucial role of Smad3 is further supported by animal experiments with reconstitution of GFP+ Smad3−/− bone marrow on Smad3+/+ mice and adoptive transfer of Smad3−/− NK1.1+ cells into B16F10 tumour-bearing NOD/SCID mice." (PMID 28262747, 2017). "Several reports using genetically modified mouse models highlight the importance of TGFB superfamily signaling components, such as INHA, SMAD3, SMAD1/5, and BMPR1A/BMPR1B, in sex cord-stromal tumor development." (PMID 29221447, 2017). "SMAD3, as a major mediator of TGF-β signaling, activates TGF-β-induced EMT, promotes EMT and tumor invasion." (PMID 28611292, 2017). "The TGFβ signal mediator SMAD3 is phosphorylated in mice with 4T1 OCIB and that the relative expression of Nox4 mRNA and Nox4-RyR1 binding is higher than in non-tumor control mice." (PMID 29312148, 2017). "Myostatin and Smad3 phosphorylation were also similar in control, vehicle, and (+)-JQ1-treated muscles from C26-tumor-bearing mice." (PMID 29167426, 2017). "Interestingly, mice that received E4BP4 knockdown Smad3−/− NK cells (siE4BP4) exhibited a higher tumour growth rate, which was associated with lower levels of infiltrating NK1.1+CD3− NK cells and the expression of NKp46 when compared with those that received siT-bet Smad3−/− NK cells." (PMID 28262747, 2017). "In vitro analyses have shown a tumor suppressor role of miR-145, where miR-145 inhibits TGF-β-induced epithelial-mesenchymal transition and invasion through the repression of SMAD3 and TGFBR2 in NSCLC cells." (PMID 28915579, 2017). "In contrary, in later stages, TGF-β has tumor-promoting role, activating transcriptional factors Smad3/4 and Wnt, supporting EMT and stemness of tumor cells." (PMID 27630452, 2016). "Ser-213 phosphorylation of Smad3 indirectly inhibits its COOH-terminal phosphorylation and subsequently suppresses tumor-suppressive pSmad3C signaling." (PMID 26771649, 2016). "Here, we show that these opposing effects are a result of the synergy between SMAD3, a downstream effector of TGF-β signaling, and the distinct epigenomes of breast-tumor-initiating cells (BTICs)." (PMID 26686634, 2015). "It functions as a tumor suppressor gene and interacts with several transcription factors like JUND, NFKB, SMAD3 etc.." (PMID 26307114, 2015). "The SMAD2 and SMAD3 transcription factors lie at the core of the transforming growth factor (TGF) pathway, which promotes tumor invasion and Epithelial-Mesenchymal Transition (EMT)." (PMID 26356815, 2015). "Linker phosphorylation of Smad3 indirectly inhibits its COOH-terminal phosphorylation and subsequently suppresses tumor-suppressive pSmad3C signaling." (PMID 25050845, 2014). "IBD scores at study end points were reduced compared with Smad3−/− mice and were similar to IBD scores in WT mice; tumor occurrence was rare in Smad3+/− mice." (PMID 24244446, 2013). "For instance, immunomodulators that have the capacity to induce IL-12 and IFN-γ with novel SMAD3/4 or STAT3 and STAT6 inhibitory molecules are potential targeted mixtures of polarizing the beneficial immune cells within tumor microenvironment." (PMID 21943203, 2011). "SMAD3 and SMAD4 mRNA expression levels were found to be significantly elevated in the tumor tissues compared to normal tissues for four of five probes (> 5-fold average increase, P < 0.05) and one of two probes (> 10-fold increase, P < 0.01)." (PMID 21835029, 2011). "TGFBR2, SMAD3, SMAD5, SOS1 and SOS2 were found to be lower expressed in VEGFA165 tumours compared with control tumours." (PMID 22045186, 2011). "CoCM induced higher Smad3- and Smad2-mediated luciferase activity than did TuCM, FbCM, or medium, demonstrating that CoCM derived TGF-β increases TGF-β signaling in tumor cells." (PMID 20352126, 2010).